APOB (apolipoprotein B)
Diseases named in the same sentence as APOB in open-access papers (continued):
Sharing a sentence is not in itself a finding about the gene and the disease.
atherosclerosis (continued). "Therefore, we speculate that the use of specific Ox-ApoB fragments for immune intervention can reduce the deposition of Ox-LDL in endothelial cells can prevent the destruction of the endothelial junction barrier and thereby inhibit the progression of atherosclerosis." (PMID 35391927, 2022). "Continuous delivery of a low-dose ApoB–peptide mix (p210, p240, and MDA-p210) without adjuvant over 2 weeks via subcutaneously implanted minipumps significantly reduced atherosclerosis in Apoe−/− mice through induction of a Treg response." (PMID 33266027, 2020). "Lastly, utilization of a T cell restimulation assay and an innovative MHC-II-tetramer loaded with an ApoB-epitope enabled direct detection of ApoB-reactive CD4+ T cells (ApoB+ T cells) in human blood from subjects with and without atherosclerosis." (PMID 33266027, 2020). "Non-HDL-C is a cholesterol carried by apolipoprotein B, including those carried by LDL-C and VLDL-C, and is considered a useful marker of atherosclerosis." (PMID 33149723, 2020). "Transgenic mice overexpressing human apoB100, the main apoB in human LDL, fed a diet containing 16% fat and 1.25% of cholesterol for 18 weeks developed severe hypercholesterolemia and atherosclerosis as compared with regular chow diet-fed non-transgenic mice." (PMID 30037080, 2018). "Non-HDL-apoC-III is an independent predictor of atherosclerosis, and LDL containing both apoB and apoC-III is more atherogenic than LDL containing apoB alone, supporting an obesity-associated increase in risk attributable to apoC-III." (PMID 28473926, 2017). "While the decreased levels of very low-density lipoprotein receptor (VLDLR), apolipoprotein B (ApoB), apovitellenin 1 (ApoVLDlII), and vitellogenin (VTGI, VTGII, and VTGIII) genes expressed in the ovary are indicative of atherosclerosis, they do not explain the disease." (PMID 41585947, 2025). "To examine the relative contribution of each key biomarker to atherosclerosis, we constructed cumulative incidence curves for ApoB, LDL-C, and LDL-TG levels against the cumulative incidence of atherosclerosis in all patients and in patients who were not on statins." (PMID 36684605, 2022). "We found that APOB, FN, MBL2, and miR-340 could be involved in atherosclerosis formation in IS but not in MI, suggesting different processes underlying ischaemia, depending on the affected organ." (PMID 33374290, 2020). "In line with these suggestions that PCSK9 exerts LDL-R-independent effects related to atherosclerosis, a triple knockout mouse with PCSK9−/−, LDL-R−/−, and ApoB−/− revealed less atherosclerosis than an LDL-R−/− and ApoB−/− double knockout mouse without any differences in cholesterol levels." (PMID 33364976, 2020). "We conclude that apoB and CRP, but not LDL-cholesterol predicted subclinical atherosclerosis." (PMID 23536999, 2013). "We found that apoB/non-HDL-C was a distinct biomarker for nAMD and non-pachy PCV, indicating that 1) non-pachy PCV may share pathological similarity with nAMD 2)nAMD and non-PCV closely correlated with age-related atherosclerosis." (PMID 35928899, 2022). "Whilst it is not known whether increased apolipoprotein-B levels are directly induced by type I IFN, such a probability remains, providing an additional mechanism by which type I IFN might contribute to the pathogenesis of atherosclerosis." (PMID 23966997, 2013).
dyslipidemia (460 papers, 2006 to 2026). "Metabolic syndrome is closely associated with dyslipidemia, characterized by elevated plasma triglycerides and apolipoprotein B on one side, and lower HDL cholesterol on the other." (PMID 41465047, 2025). "An increase in the apolipoprotein B (APOB) to APOA1 ratio is associated with the worsening of metabolic syndrome (MetS) components in PCOS, including IR, elevated androgen levels, and increased liver enzyme levels." (PMID 40083347, 2025). "ApoB rs512535 major G allele homozygotes were found to have an enhanced risk of metabolic syndrome (MetS)." (PMID 40597178, 2025). "The excessive secretion of the apolipoprotein B48 (ApoB48) is the main cause of postprandial dyslipidemia." (PMID 40006605, 2025). "The potential confounding effects of associated risk factors, such as elevated apolipoprotein B, insulin resistance, and metabolic syndrome, are considered." (PMID 38288833, 2024). "Rates of pre-diabetes, T2D, dyslipidemia, hyperuricemia, and high-risk fasting serum Apolipoprotein B to Apolipoprotein A1 Ratios were comparable across participants, but not hypertriglyceridemia and hypertension." (PMID 39075463, 2024). "Specifically looking at premenopausal women, WC and WHtR were negatively associated with insulin resistance and positively associated with dyslipidemia (high TG and ApoB levels)." (PMID 38474854, 2024). "According to the 2019 ESC/EAS Guidelines for the management of dyslipidemia regarding lipid modification to reduce cardiovascular risk, ApoB measurements are recommended as a class I indication instead of LDL-C for primary screening, diagnosis, and management." (PMID 37892070, 2023). "In the recent guidelines, ApoB analysis is recommended as a tool for risk assessment, particularly for patients with high TG levels, diabetes, obesity, metabolic syndrome, or very low LDL-C levels." (PMID 37892070, 2023). "Apolipoprotein B (ApoB) analysis is recommended in risk assessments, particularly in people with high TG levels, DM, obesity, metabolic syndrome, or very-low LDL-C levels." (PMID 36975891, 2023). "Further prospective studies or randomized controlled trials are needed to explore the causal relationship between dyslipidemia, ApoB/ApoA-I ratio, and PSCI." (PMID 37960323, 2023). "Among metabolic syndrome patients with high plasma saturated fatty acid levels, the G allele carriers had higher plasma triglycerides, apolipoprotein C, and apolipoprotein B-48 concentrations than the CC genotype." (PMID 35276838, 2022). "In conclusion, these results indicate that common and rare APOB variants are independently associated with various lipid levels and metabolic syndrome in Taiwanese individuals." (PMID 36499290, 2022). "All four lead SNPs downstream of APOB also had strong association with metabolic syndrome (all p < 6.0 × 10−8)." (PMID 36499290, 2022). "Accordingly, scholars should explore ethnic-specific APOB variants as genetic determinants of cardiometabolic traits and metabolic syndrome in a specific population." (PMID 36499290, 2022). "The 2019 ESC/EAS guidelines for the management of dyslipidemias included for the first time apoB in the risk assessment of CAD and efficacy of lipid-lowering therapy." (PMID 35174229, 2022). "Given the significant role metabolic syndrome plays in cardiovascular risk and most participants in our study demonstrate the metabolic syndrome, the use of ApoB/ApoA1 is most germane and adds more evidence for its use in the clinical setting." (PMID 35295919, 2022). "KATP rs2285676 (A-allele) correlates with a higher risk of all subtypes [e.g., TRIG, LDL-C, ApoB and Lp(a)] of dyslipidemia except HDL-C and ApoA-I." (PMID 35402560, 2022).
dyslipidemia (continued). "We tested the association of the lead SNPs downstream of APOB with lipid profiles and metabolic syndrome." (PMID 36499290, 2022). "We further performed a regional association analysis to test the association between the APOB variants and metabolic syndrome." (PMID 36499290, 2022). "Our results demonstrate the crucial role of APOB variants in various aspects of lipid profiles and metabolic syndrome." (PMID 36499290, 2022). "In fact, several guidelines have considered apoB as the secondary target in the management of dyslipidemia and CVD risk." (PMID 35665267, 2022). "We used genome-wide CHB array data to test the association of the identified APOB mutations with lipid profiles and metabolic syndrome in the TWB participants." (PMID 36499290, 2022). "The effects of APOB locus variants on lipid profiles, metabolic syndrome, and the risk of diabetes mellitus (DM) in Asian populations are unclear." (PMID 36499290, 2022). "This study clarified the effects of common and rare APOB variants on lipid profiles and metabolic syndrome in Taiwanese individuals." (PMID 36499290, 2022). "Our results revealed a significant association between common and rare APOB variants with multiple lipid levels and metabolic syndrome." (PMID 36499290, 2022). "When testing the superiority of apoB/apoA1 over apoB alone, they found that the difference was not statistically significant when adjusting for risk factors, such as obesity, smoking, dyslipidemia, hypertension, diabetes, and high C-reactive protein (CRP)." (PMID 34677405, 2021). "In recent years, high levels of ApoB and low levels of ApoA1 have been found to be associated with the higher risk of cardiovascular disease, metabolic syndrome, ischemic stroke, and Alzheimer's disease." (PMID 34961824, 2021). "Apolipoprotein B (Apo B) is advised for the risk evaluation especially in individuals with high TG, DM, obesity or metabolic syndrome, or very low LDL-C." (PMID 33620601, 2021). "In this study, we observed that higher LDL-C levels were associated with increased levels of PDW, triglyceride, and apolipoprotein B. Dyslipidemia usually includes both elevated LDL-C and triglycerides and reduced HDL-C." (PMID 33746886, 2021). "The Apolipoprotein B gene (APOB) has been associated with dyslipidemia and a risk factor of Cardio Vascular Diseases (CVDs), especially the Coronary Artery Disease (CAD)." (PMID 34815491, 2021). "In fact, ApoB is also recommended to assess CV risk, particularly in patients with hypertriglyceridemia, diabetes, obesity, metabolic syndrome and very low LDL-c levels, and it can be used as an alternative to LDL-c for screening, diagnosis and management." (PMID 32505210, 2020). "Of note, apoB has been adversely linked to metabolic syndrome components and cardiovascular risk factors." (PMID 31936330, 2020). "The same study demonstrated that carriers of the G allele were characterized by higher plasma apoB and triglyceride (TG) levels and the presence of G allele was associated with components of metabolic syndrome." (PMID 31319591, 2019). "In conclusion, both RYGB and SG induce a significant increase in HDL and ApoA1, and a decrease in LDL, oxLDL and ApoB, in women with severe obesity and a high cardiovascular risk defined by the presence of the metabolic syndrome." (PMID 29925393, 2018). "Rs676210, a variant in APOB, had a dominant effect on the risk of dyslipidemia and was the only significant association in the logistic regression model (p=0.02)." (PMID 29126409, 2017). "In summary, chronic stress–induced ROS become intra-ER ROS that cause PDI/ERO-1α uncoupling, which results in ER stress and apoB aggregation-associated hepatic dyslipidemia." (PMID 28747775, 2017). "We found the common variant rs676210 in APOB correlated with the development of dyslipidemia, the presence of the minor allele (A) being protective for the outcome." (PMID 29126409, 2017).
dyslipidemia (continued). "The apoB XbaI polymorphism (X) was selected for the present study by virtue of its documented association with obesity and dyslipidemia elsewhere." (PMID 25889118, 2015). "The INTERHEART study reported that metabolic risk factors such as atherogenic dyslipidemia (abnormal apolipoprotein A/apolipoprotein B ratio), truncal obesity, hypertension and diabetes are most important cardiovascular risk factors in South Asians." (PMID 25969733, 2015). "Several polymorphisms at the APOB locus, including the 3611 MspI polymorphism in the promoter region and a truncating mutation, have been shown to associate with dyslipidemia in humans." (PMID 26121138, 2015). "Recently, several studies have reported that the apoB/apoA1 ratio is associated with metabolic syndrome in different ethnical groups." (PMID 24886173, 2014). "Studies have indicated that IR was significantly associated with ApoB/ApoA-I ratio, metabolic syndrome (MetS), and lipid indices." (PMID 24949011, 2014). "The pattern of dyslipidemia associated with psychosis here therefore requires further investigation in other samples, including assessment of ApoB, remnant like particles and small dense LDL-c which SHIP did not measure." (PMID 24367528, 2013). "Visceral adiposity is known to be associated with an elevated ApoB/ApoA1 ratio with is considered to be a risk factor for metabolic syndrome." (PMID 23442518, 2013). "ApoB-deficient human patients, and patients with dyslipidemia suffer from various abnormalities in peripheral tissues." (PMID 22844248, 2012). "Increased intestinal synthesis of CM and of their major protein component, apolipoprotein B48, have been identified as important contributors to the dyslipidemia associated with insulin-resistant and diabetic states." (PMID 20463919, 2010). "This is a probable cause that helps apoB retain their credibility as a marker of dyslipidemia as much as treatment target for statin therapy, since they ‘represent’ these atherogenic small, dense LDL." (PMID 19690648, 2007). "Additionally, a retrospective study indicated that NHHR offers superior diagnostic value for metabolic syndrome compared to commonly used metrics like apolipoprotein B/apolipoprotein A1 ratios." (PMID 40084133, 2025). "In our study, although we did not observe a significant potential impact of blood lipids on the gut microbiota, it is important to note that certain genetic variations, such as the APOB rs693, may serve as an independent risk for dyslipidemia." (PMID 38431594, 2024). "Moreover, the impact of adding ApoB testing to the assessment of dyslipidemia prevalence and CVD risk in the Korean population has been less explored compared to Western populations." (PMID 38535329, 2024). "Postprandial dyslipidemia following a high-fat meal in BMI-matched healthy subjects, as well as in individuals with prediabetes or type 2 diabetes, has been associated with an increase in TGs and ApoB concentrations." (PMID 38393015, 2024). "Cholesterol stimulates eosinophilic inflammation, leading to a predisposition to atopy, and the link between ApoB and FeNO found in this analysis may suggest an association between dyslipidemia and eosinophilic airway inflammation." (PMID 38999820, 2024). "Evidence shows that arachidonic acid is associated with dyslipidemia and cholesterol-associated lipoprotein metabolism and that arachidonic acid increased plasma concentrations of TC and ApoB, as well as elevated ApoB protein expression and decreased protein expression of ABCG5/8 in mice." (PMID 39372201, 2024). "Although several studies have investigated risk factors for dyslipidemia, such as diet, obesity, and lifestyle, few studies have extensively investigated the relationship between insomnia and abnormal apolipoprotein levels (including ApoA-1, ApoB and LPA)." (PMID 38087303, 2023).
dyslipidemia (continued). "ESC/EAS 2019 guidelines state that apoB analysis is recommended as secondary lipid analysis for risk evaluation, especially for patients who have high TG levels, diabetes mellitus, obesity, metabolic syndrome or very low LDL-C levels." (PMID 35371605, 2022). "Lind also revealed that APOB rs673548 was associated with an increased risk of metabolic syndrome." (PMID 36499290, 2022). "Many studies have found an association of ApoA1 and ApoB in obesity and metabolic syndrome." (PMID 35558744, 2022). "As a result, the European Society of Cardiology/European Atherosclerosis Society 2019 guidelines for the management of dyslipidemia recommended measurement of apoB levels to estimate ASCVD risk and to assess the clinical benefits of using lipid-lowering therapy." (PMID 35371605, 2022). "ApoB may be useful in predicting CVD risk in states of insulin resistance such as metabolic syndrome and type 2 diabetes." (PMID 34677405, 2021). "In addition, ApoB-related dyslipidemia is linked to nonalcoholic fatty liver disease (NAFLD), a silent pandemic affecting billions globally." (PMID 34236046, 2021). "Children with OB are at almost two times the risk of high ApoB (OR = 1.97), and around two and a half times the risk for high TG (OR = 2.45), low ApoA1 (OR = 2.57), and dyslipidemia (OR = 2.54), and more than four and half times the risk for low HDL (OR = 4.75)." (PMID 34886385, 2021). "This unfavorable CVD profile is characterized by an elevated risk of dyslipidemia, high apolipoprotein B/apolipoprotein A1 ratio, hypertension, glucose intolerance, type 2 diabetes mellitus, as well as increased BMI, body fat percentage, abdominal and visceral adiposity." (PMID 30488037, 2018). "Despite the lack of association between the APOB rs11279109 with hypertension and dyslipidemia in this study, the role of other polymorphisms at the APOB gene locus or other loci may be contributing to this pathogenesis." (PMID 29362515, 2017). "Several studies have identified APOB as a candidate gene predisposing individuals to dyslipidemia." (PMID 25292352, 2014). "Based on our current observations, more optimal management of dyslipidemia in subjects with PAD may lower cardiovascular risk by favorably improving several apolipoprotein subparticles in addition to apoB." (PMID 24102029, 2013). "In particular, the task force team suggested that the apoB level may provide a better estimate of the concentration of atherogenic particles, especially in high risk patients with diabetes or metabolic syndrome, than other lipid markers." (PMID 23284722, 2012). "With respect to LDL-C and non-LDL-C therapeutic targets, a recent joint Consensus Statement (American Diabetes Association and American College of Cardiology Foundation) suggests new treatment goals for apoB in patients with atherogenic dyslipidemia and cardiometabolic risk." (PMID 21356116, 2011). "More recently, the latest guideline for dyslipidemia management underlined the atherogenic effect of apoB and revealed that the clinical benefit of lipid-lowering therapy might attribute to the reduction of apoB-containing particles, which mostly referred to RC." (PMID 32631321, 2020). "Furthermore, SNPs at APOB rs693 resulting in amino acid substitution and SNPs at rs104203, which result in a silent mutation, have been reported to be associated with dyslipidemia (Tsunoda, Harihara, Tanabe, & Dashnyam, 2012) and an increased risk of breast cancer in Chinese individuals." (PMID 32243098, 2020). "The apoB/apoA-I ratio remained significantly related to cancer mortality (HR: 1.17; 95% CI 1.09–1.25), even after adjusting for traditional risk factors (age, sex, race, alcohol and dietary intake, smoking, BMI, dyslipidemia, hypertension, and diabetes) and CRP." (PMID 31936330, 2020).